SLC7A5 (solute carrier family 7 member 5)
Diseases named in the same sentence as SLC7A5 in open-access papers (continued):
Sharing a sentence is not in itself a finding about the gene and the disease.
cancer (continued). "The transporters for glutamine and essential amino acids, ASCT2 (solute carrier family 1 member 5, SLC1A5) and LAT1 (solute carrier family 7 member 5, SLC7A5), respectively, are overexpressed in aggressive cancers and have been identified as cancer-promoting targets." (PMID 29326164, 2018). "In addition, SLC7A5 (regulated by miR-7-5p), SLC16A1 (regulated by miR-124-3p), and SLC40A1 (regulated by miR-485-3p) genes, belong to the transmembrane solute transport (SLC) and are involved in chemoresistance in many of the cancers studied here." (PMID 40061896, 2025). "Additionally, an analysis of cancer stages revealed a significant correlation between the expression levels of SLC3A2, BSG, SLC7A5, SLC7A6, LCN2, and SLC7A9 and the pathological stages of ACC, with p-values of 0.28, 0.468, 0.00799, 0.0237, 0.0359, 0.264, 0.193, 0.81, and 0.0246, respectively." (PMID 40566559, 2025). "miR-7-5p/ABCC1/SLC7A5, miR-107/RAD51, miR-124-3p/ABCC4/SLC16A1/MGMT, miR-212-3p/ABCG2, miR-381-3p/GJA1 and miR-485-3p/SLC40A1 may modulate pathways that confer chemoresistance to cancer cells." (PMID 40061896, 2025). "The solute carrier family 7 member 5 (SLC7A5; LAT1), which especially participates in the transport of large neutral amino acids, is extraordinarily upregulated in hepatocellular carcinoma, and suppression of SLC7A5 leads to downregulates global translation in cancer cells." (PMID 39698464, 2024). "In addition to activating mTORC1, SLC7A5 can also facilitate MYC and EZH2 signaling in cancer cells, while SLC3A2 has also been confirmed to facilitate uncontrolled proliferation of cancer cell through AKT, MAPK, and cell cycle-related P21/P27 signaling pathways." (PMID 38267663, 2024). "The SLC36A1, SLC7A5, SLC7A8 genes, which are related to amino acid transmembrane transporter activity, could play a role in tumour uptake of amino acids produced by host protein degradation during cancer cachexia and contribute to the growth of tumors." (PMID 36428623, 2022). "In conclusion, miR-126 decreases proliferation and mammosphere formation of MCF-7, ER+ BC cell line, which suggests that this miR might play a tumor suppressor role in ER+ breast cancer through potentially targeting SLC7A5 (LAT1), a sodium-independent transporter overexpressed in cancer." (PMID 35328298, 2022). "However, in cancer types in which SLC7A5 is co-expressed with TDO and not with IDO (colon and rectum adenocarcinomas, lung adenocarcinoma and lung squamous cell carcinoma), AhR activation is likely to involve only TDO activity." (PMID 36286592, 2022). "These upregulated target genes are enriched for the pathways involved in metabolism (e.g., SLC3A2, SLC7A5) and mitochondrial gene expression (e.g., PNPT1), consistent with previous studies, demonstrating that elevated MYC/MYCN induces metabolic reprogramming in cancer cells." (PMID 32060267, 2020). "Two significantly enriched pathways in LUAD and their related DEmRNAs, namely transcriptional misregulation in cancer (TGFBR2, FLI1, ERG and SIX1) and central carbon metabolism (NTRK3 and SLC7A5), were speculated to play key roles in LUAD regulated by DEmiRNAs." (PMID 30761256, 2019). "The induction of apoptosis by the inhibition of SLC7A5 or dietary L-Leu restriction is a mechanism that might contribute to control CD4 T cell-mediated immune response which has not been described previously, although this effect has been well documented for cancer cells." (PMID 40399490, 2025). "SLC7A5-specific PET probe FAMT has been shown to be cancer-specific, distinguishing cancer from non-cancerous lesions, including inflammation." (PMID 38790003, 2024). "To explore potential interactions between cancer cells with different expression level of SLC7A5 and other cells in TNBC, we divided cancel cells into SLC7A5-positive (count>0) and SLC7A5-negative cancer cells (count=0) based on the expression level of SLC7A5." (PMID 37731509, 2023).
cancer (continued). "Unlike SLC7A5, SLC7A8 lacks studies that illustrate its prognostic role in human cancer." (PMID 32200487, 2020).
tumor (191 papers, 2008 to 2026). "Our results highlight for the first time that SLC7A5-deficient allogenic T cells fail to reject tumor due to impairment in activation, proliferation and GzmB and IFNy expression." (PMID 40399490, 2025). "Similar to HIF-1α, HIF-2α can induce the expression of SLC38A2, SNAT2, SLC1A5 variant, GLS1, and SLC7A5, which can facilitate the rapid growth of tumor cells." (PMID 38172980, 2024). "High SLC7A5 expression was associated with resistance to chemotherapy in breast and other tumor types." (PMID 38256136, 2024). "We observed that high expression of the SLC7A5 gene, encoding a plasma membrane amino acid transporter, was associated with tumor recurrence." (PMID 38256136, 2024). "In the BLCA immunotherapy cohort IMvigor210, SLC7A5 was significantly associated with the staging of the tumor." (PMID 38790003, 2024). "L-type amino acid transporter 1 (LAT1), also referred to as SLC7A5, is believed to regulate tumor metabolism and be associated with tumor proliferation." (PMID 35177712, 2022). "In principle, therapeutic targeting of SLC7A5 would offer an opportunity to unleash the functional association between MYC and SLC7A5, leading to tumour suppression." (PMID 34195095, 2021). "On the other hand, it has been shown that HIF-2α regulates mTORC1 activity in VHL-deficient tumour cells through the transcriptional control of the amino acid transporter Slc7a5." (PMID 29671738, 2018). "High SLC7A5 mRNA expression was significantly associated with larger tumour size (p < 0.001), higher grade (p < 0.001), positive nodal metastasis (p< 0.001) and poor NPI (p < 0.001)." (PMID 29566741, 2018). "SLC7A5 mRNA and protein expression was significantly associated with the expression of the key regulator of tumour cell metabolism, c-MYC, specifically in luminal B tumours only (p = 0.001)." (PMID 29566741, 2018). "We found that high SLC7A5 expression is associated with GC clinicopathologic features such as tumor size, lymph node metastasis, local invasion and TMN stages." (PMID 27846244, 2016). "As a result, we found that SLC7A5 was associated with the inflammatory tumor microenvironment." (PMID 38790003, 2024). "By integrating bulk transcriptome data, we developed a clinical scoring model based on TP63 and SLC7A5, which are closely associated with tumor stage, revealing the significant prognostic efficacy of the TP63+ SLC7A5+ HNSCC-mediated ferroptosis mechanism in HNSCC patients." (PMID 39234254, 2024). "Therefore, we concluded that the glutamine metabolism-associated gene SLC7A5 promotes TNBC tumor growth and metastasis." (PMID 37731509, 2023). "In addition, the levels of LINC01614 in primary CAFs positively associated with the mRNA levels of SLC38A2 and SLC7A5 in the paired LUAD tumor cells." (PMID 36209111, 2022). "This indicates that residual SLC7A5 activity may allow normal cell function in SLC3A2-deficient tumor cells." (PMID 33953707, 2021). "The current study included two large discovery and validation cohorts to confirm the significant association between the high SLC7A5 protein expression and the poor prognostic clinico-pathological parameters, including larger tumour size, higher grade and poor NPI." (PMID 29566741, 2018). "Both SLC7A5 mRNA and SLC7A5 protein were associated with medullary-like tumours." (PMID 29566741, 2018). "Importantly, Slc7a5 deletion sensitises Kras tumours to rapamycin (further suppressing mTORC1 signalling) causing tumour cells to undergo growth arrest." (PMID 30405205, 2018). "The expression of SLC7A5 cationic amino acid transporter was also found to be significantly associated with cell proliferation and angiogenesis, moreover it seems to play an important role in enhancing the tumor growth in vivo." (PMID 23155391, 2012).
tumor (continued). "SLC7A5 appears to have a pivotal role in this regulatory axis, as its expression was highly associated with the enzymes that mediate glutamate degradation to form the amino acid proline, which has been shown to play a role in assisting tumour growth by different mechanisms." (PMID 29566741, 2018). "Through invasion, migration, apoptosis, and xenograft tumor model, the study confirmed the impact of SLC7A5 on the malignant progression of oxaliplatin-resistant GC cells." (PMID 40133832, 2025). "In vivo, knockdown of SLC7A5 and administration of oxaliplatin significantly reduced tumor volume and weight in mice compared to oxaliplatin alone." (PMID 40133832, 2025). "This reprograms glutamine metabolism by upregulating transporters solute carrier family 38 member 2 (SLC38A2) and solute carrier family 7 member 5 (SLC7A5), boosting glutamine uptake to fuel tumor growth." (PMID 41409273, 2025). "Central to maintaining normal cellular growth and metabolism, SLC7A5 assumes pivotal roles, particularly in the proliferation and viability of tumor cells." (PMID 40729322, 2025). "Of note, we found more pronounced upregulation of SLC1A5 and SLC7A5 in tumor tissues compared to BPH in response to GLS1 inhibition." (PMID 40707944, 2025). "Knockdown of SLC7A5 obviously decreased the viability, migration, and invasion of oxaliplatin-resistant GC cells in vitro and tumor growth in vivo." (PMID 40133832, 2025). "miR-184 acted as a tumour suppressor, reducing metastatic potential, inducing apoptosis and cell cycle arrest, enhancing chemosensitivity by directly targeting SLC7A5, limiting its downstream effects." (PMID 41379397, 2025). "LAT1, a protein encoded by SLC7A5 and a member of the same family as SLC7A7, is critical for tumor angiogenesis by regulating cell proliferation, translation, and pro-angiogenic VEGF-A signaling." (PMID 40075158, 2025). "SLC1A5, SLC7A5, and SLC3A2 are the most highly expressed genes encoding amino acid transport proteins in the tumor microenvironment." (PMID 40438606, 2025). "Binds Annexin A2/p65 to activate NF-κB, upregulating SLC38A2/SLC7A5 to enhance glutamine uptake in tumor cells." (PMID 41409273, 2025). "CAFs can transfer METTL3 to tumor cells via secreted factors and exosomes, elevating intracellular m6A levels and altering gene expression profiles such as SLC7A5 to support tumor growth." (PMID 40740874, 2025). "Tumor cells can modulate SLC7A5 expression to alter immune cell function and evade immune surveillance." (PMID 40575157, 2025). "The coexpression of SLC1A5, SLC7A11 and SLC7A5 proteins has yet to be determined in BC and is therefore important for understanding the potential transport of Gln in and out of tumour cells." (PMID 39843491, 2025). "The results of the vivo experiment showed that the tumor volume and weight of mice in the sh-SLC7A5 group were significantly reduced, indicating that knocking down SLC7A5 inhibited the growth of MKN45R and HGC27R cells in vivo." (PMID 40133832, 2025). "More importantly, among patients receiving endocrine therapy alone, those with SLC7A5+/SLC3A2+ tumours experienced poorer prognosis, higher recurrence and mortality rates." (PMID 41154605, 2025). "Several glutamine transporters have been confirmed to be widely upregulated in cancer and are associated with tumor invasion and metastasis, such as SLC1A5 (ASCT2), SLC7A5 (LAT1), and SLC6A14." (PMID 41040664, 2025). "Limiting dietary L-Leu intake is a promising strategy to avoid SLC7A5-mediated allogenic T cell expansion and aGVHD while reducing tumor growth and further preserving GVT response." (PMID 40399490, 2025). "F. nucleatum was prevalent in tumor tissues and promoted tumor progression and radioresistance through the SLC7A5/leucine–mTORC1 axis." (PMID 41216129, 2025). "SLC7A5 facilitates the influx of large neutral amino acids, including tryptophan, thereby sustaining the metabolic demands of proliferating tumor cells and further feeding immunosuppressive metabolism." (PMID 41179282, 2025).
tumor (continued). "As SLC7A5 is a key transporter of large neutral amino acids (LNAAs), the overexpression of SLC7A5 in tumour cells depletes amino acids in the TME and restricts the function of CD8+ T cells." (PMID 40860147, 2025). "In the realm of oncology, SLC7A5 has emerged as a promising therapeutic target across various malignancies owing to its involvement in modulating amino acid equilibrium within tumor cells, thereby impacting cell proliferation and metastasis." (PMID 40729322, 2025). "There is still uncertainty as to the relationship between SLC7A5 and prognosis, tumor immune microenvironment, and therapeutic response in patients with BLCA." (PMID 38790003, 2024). "Intriguingly, it was found that SLC43A2 and SLC7A5 are expressed by tumor cells, but T cells mostly expressed SLC7A5." (PMID 38705513, 2024). "A recent investigation has documented that the inhibition of the glutamine transporter, specifically the carrier family 7 member 5 (SLC7A5), in conjunction with anti-PD-L1 treatment, significantly augments the immune response within the tumor microenvironment." (PMID 38397971, 2024). "In order to further simulate the in vivo environment, we constructed a bladder transplantation tumor model and found that overexpression of SLC7A5 significantly inhibited tumor growth." (PMID 38790003, 2024). "Elevated SLC7A5 expression correlates with larger tumor size, higher grade, distant metastases, and poor prognosis in estrogen-positive and HER2-positive BC subtypes." (PMID 38256136, 2024). "As a result, more SLC7A5 was located in in the membrane to transport leucine, which activated the mTOR pathway and ultimately accelerated tumor growth." (PMID 38556586, 2024). "This contradicted the previous results showing that overexpression of SLC7A5 promoted tumor proliferation, invasion, and migration." (PMID 38790003, 2024). "An obvious example is that JPH203/KYT-0353, an inhibitor of SLC7A5, can clinically suppress tumor growth." (PMID 39161963, 2024). "The combined application of JPH203-mediated SLC7A5 blockade and anti-PD-1 antibody significantly increased the infiltration rate of immune cells and inhibited tumor progression." (PMID 38790003, 2024). "In NSCLC, it was demonstrated that nicotine increases the expression level of the SLC7A5 gene through EGFR/SERPINB5/TRIM29/NF-κB/c-Myb pathway to increase tumor progression." (PMID 38705513, 2024). "SLC7A5 knockdown reduced mTOR pathway activity and suppressed the proliferation and metastasis of tumor cells." (PMID 39698464, 2024). "The enhanced JunD subsequently activates the transcription of SLC7A5 which promotes the tumor cells proliferation and avoids immune attack." (PMID 38402198, 2024). "SLC7A5 was overexpressed in LUAD and significantly correlated with the Ki-67 labeling index, which can increase metabolic activity and is associated with tumor cell growth." (PMID 38244585, 2024). "Overall, we discovered a unique self-protection mechanism evolved by malignant cells: TP63 regulates SLC7A5 to inhibit ferroptosis, sustain tumor growth and development, and resist immunotherapy." (PMID 39234254, 2024). "Since SLC7A5 was a key transporter of large neutral amino acids (LNAAs), overexpression of SLC7A5 on tumor cells depleted amino acid in microenvironment and restricted CD8+ T cells function." (PMID 38402198, 2024). "Several immunotherapy positive gene features, as well as tumor immune features, were positively correlated with SLC7A5." (PMID 38790003, 2024). "ALYREF silencing decreased SLC7A5 expression and subsequently inactivated mTORC1 pathway, resulting in decreased tumor proliferation." (PMID 38402198, 2024). "We observed that stable knockout of SLC3A2 and SLC7A5 effectively inhibited tumor growth in vivo, as reflected by a significant reduction in tumor size and growth rate compared to non-target CRISPR-V2 controls." (PMID 38267663, 2024).
tumor (continued). "To investigate the therapeutic efficacy and immune microenvironment remodeling realized through targeted SLC7A5 and anti-PD-1 agent combination therapy in vivo, we established 4T1 subcutaneous fat pat tumor models." (PMID 37731509, 2023). "SLC7A5, an important transporter, has been demonstrated to mediate the uptake of amino acids in tumours and T cells, and it has been confirmed that SLC7A5-mediated metabolic reprogramming plays a major role in macrophages polarization." (PMID 37491279, 2023). "SLC7A5 has been reported to be overexpressed in TNBC due to its glutamine transporting activity to tumor cells for energy production—TNBC is thus glutamine dependent and requires glutaminase for its catabolism." (PMID 37900178, 2023). "Among these six hub genes, DEPTOR, DPEP1, NAT8, and SUSD2 were expressed at their highest levels in normal tissues, whereas PLOD2 and SLC7A5 were expressed at their highest levels in tumor thrombi." (PMID 37328520, 2023). "SLC7A5 downregulation led to a relatively lower tumor weight and volume and a decreased number of metastatic nodules formed in pulmonary tumor lesions compared with those in the negative control mice." (PMID 37731509, 2023). "For example, SLC7A5 is reported to involve in tumor cell metabolism and promotes cell proliferation." (PMID 37303949, 2023). "Collectively, these results suggested that SLC7A5 knockdown attenuates tumor progression and immune suppression in TNBC." (PMID 37731509, 2023). "In a hypoxic microenvironment, upregulated SLC7A5 expression contributes to the accumulation of methionine in tumor cells, which leads to methionine depletion in the TME." (PMID 37545500, 2023). "SLC7A5, as an important amino acid transporter, is essential for the uptake of amino acids by tumor cells." (PMID 37731509, 2023). "LLGL2 was expressed in the cytoplasm and SLC7A5 in the plasma membrane, indicating co-expression in the same tumor cells." (PMID 36192404, 2022). "According to TCGA-BRCA data, the expression of the positive genes of risk score (HJURP, IFI27, RAD51AP1, EZH2, DNMT3B, SLC7A5, DBF4 and USP18) in tumors was higher than that in normal and tumor-adjacent tissues." (PMID 36341435, 2022). "Consistently, lentivirus-mediated overexpression of SLC7A5 obviously rescued the inhibitory effect of cholesterol-modified si-circARID1A on the growth of HGC-27 cells-derived tumor xenograft." (PMID 35986300, 2022). "SLC1A5 and SLC7A5 have been identified as potential therapeutic targets in cancer metabolism because of their significance in tumor metabolism." (PMID 35757505, 2022). "In vivo experiments further showed that downregulation of SLC7A5 inhibited tumor growth (sFigure 2) All of these results confirmed that SLC7A5, as an oncogenic gene, can mediate the development of KRAS mutant tumors." (PMID 36505791, 2022). "Immunohistochemistry also validated expressions of SLC1A5 and SLC7A5 in MM tumor specimens from both mouse xenografts, S1C) and MM patients." (PMID 35036082, 2022). "recently reported that LLGL2 promoted leucine uptake and conferred tumor growth and resistance to tamoxifen treatment by increasing the cell surface levels of SLC7A5 in Erα-positive breast cancer." (PMID 36192404, 2022). "Only for advance NSCLC, high vs. low tumour folate was significantly associated with the overexpression of MCT1, MCT4, LDHA, SLC7A5, SIRT3, and GLUD1." (PMID 36615660, 2022). "As transporters including SLC7A5 also transport Kyn, they can contribute further to its influx into tumours, thereby bypassing IDO, TDO and FAMID, activating the AhR, further enhancing IDO expression, and undermining invading T-cell function." (PMID 36286592, 2022). "The results showed that SLC7A5 fluorescence intensity was significantly decreased (sFigure 2D), and the growth rate of the tumor was slower than that of the control group (sFigures 2E–G)." (PMID 36505791, 2022).